METTL14 (methyltransferase 14, N6-adenosine-methyltransferase non-catalytic subunit)
Diseases named in the same sentence as METTL14 in open-access papers (continued):
Sharing a sentence is not in itself a finding about the gene and the disease.
coronary heart disease (5 papers, 2021 to 2024). "Here, we observed that the levels of m6A modification and Mettl14 were increased in the peripheral blood mononuclear cells of patients with coronary heart disease and LPS-stimulated THP-1 cells." (PMID 35598196, 2022). "Herein, we showed that the expression of the m6A modification “writer” Mettl14 was increased in coronary heart disease and LPS-stimulated THP-1 cells." (PMID 35598196, 2022). "Our study demonstrates that Mettl14 attenuates cardiac I/R injury by activating Wnt/β-catenin in an m6A-dependent manner, providing a novel therapeutic target for ischemic heart disease." (PMID 35004673, 2021). "Therefore, Mettl14 might serve as a promising therapeutic target for ischemic heart disease." (PMID 35004673, 2021).
endometrial tumors (5 papers, 2020 to 2024). "In addition, ∼70% of endometrial tumors exhibited reductions in m6A methylation that are due to either METTL14 mutation (R298P) or decreased METTL3 expression." (PMID 34906165, 2021). "In endometrial tumors, reduced METTL3 expression or METTL14 mutation causes reduced levels of m6A, leading to enhanced cell proliferation, colony formation, migration, and invasion of tumor cells." (PMID 39457524, 2024).
hepatoblastoma (5 papers, 2022 to 2024). Hepatoblastoma (HB) is a malignant hepatic tumor and is the most common pediatric liver cancer. "Another study has suggested a potential correlation between METTL14 polymorphisms and hepatoblastoma susceptibility, offering a fresh perspective on the genetic factors underlying m6A modification in hepatoblastoma." (PMID 38390281, 2024). "We have previously shown that several RNA m6A-mediated genes (i.e., METTL3, METTL14, WTAP, YTHD1, YTHDC1, and ALKBH5) are associated with hepatoblastoma susceptibility." (PMID 35986847, 2022). "Moreover, one study reported that crosstalk between METTL14 and miR-186 regulates hepatoblastoma progression by means of the Wnt/β-catenin signaling pathway." (PMID 36936652, 2023).
lymph node metastasis (5 papers, 2020 to 2025). "The results indicated that lower expression levels of METTL3 and METTL14 were associated with increased lymph node metastasis (N1‐N2), enhanced distal metastasis (M1), and poorer patient survival." (PMID 40785027, 2025). "Furthermore, downregulated expression of METTL14 was significantly associated with Lymph node metastasis(P = 0.018), distant metastasis(P = 0.002) and TNM stage(P = 0.005)." (PMID 32552762, 2020). "We further analysed the correlation between METTL14 expression and gender, age, differentiation, T stage, and lymph node metastasis." (PMID 34900689, 2021). "The expression of METTL3, METTL14, WTAP, YTHDC2, YTHDF1, and YTHDF2 was remarkably higher in CRPC with lymph node metastasis than in CRPC with bone metastasis, whereas ALKBH5, FTO, and YTHDF3 were substantially decreased in CRPC with lymph node metastasis." (PMID 33403026, 2021).
rheumatoid arthritis (5 papers, 2023 to 2025). A chronic, systemic autoimmune disorder characterized by inflammation in the synovial membranes and articular surfaces. "For example, METTL14 promotes the activation of fibroblast‐like synoviocytes (FLS) through the LASP1‐SRC‐AKT axis in rheumatoid arthritis." (PMID 41316520, 2025). "For example, it has been reported that METTL14 regulates TNFAIP3 expression via m6A-related mRNA stability and involved the inflammatory response of active rheumatoid arthritis." (PMID 38355483, 2024).
skin cancer (5 papers, 2022 to 2024). "In contrast to its oncogenic effect, METTL14 was found to trigger ferroptosis in endocervical cancer, impede the tumor growth of ocular melanoma, and promote genome-wide repair to prevent skin cancer, acting as a tumor suppressor." (PMID 39563370, 2024). "In skin cancer, METTL14 was also found to promote cell proliferation, as knockdown of Mettl14 in human keratinocytes resulted in decreased cell proliferation; however, the mechanism by which METTL14 promotes proliferation in this context remains unclear." (PMID 35350378, 2022). "UVB radiation downregulates METTL14 protein expression through NBR1 autophagy cargo receptor (NBR1)-dependent selective autophagy, further reducing global genome repair (GGR) and translation of DDB2 transcripts and inducing the development of skin cancer." (PMID 38473842, 2024). "Notably, METTL14 has been reported to be required for some cancer development, whereas METTL14 activation shows more tumor‐suppressive activity in a variety of tumors including UCEC, LIHC, GBM, and skin cancer." (PMID 36794620, 2023). "Conversely, in keratinocytes and skin cancer cells, METTL14 promoted migration in an m6A dependent manner, as knockdown of Mettl14 decreased migration, while overexpression of wild-type, but not catalytically inactive mutant, Mettl14 resulted in increased migration." (PMID 35350378, 2022).
triple-negative breast carcinoma (5 papers, 2020 to 2024). An invasive breast carcinoma which is negative for expression of estrogen receptor (ER), progesterone receptor (PR), and human epidermal growth factor receptor 2 (HER2). "Six paired samples from two luminal B, two Her2 enriched, and two triple-negative breast cancer (TNBC) patients were used for IHC of METTL3, METTL14, FTO, YTHDF1, and YTHDF3." (PMID 34804948, 2021). "High METTL14 expression was more common in luminal A and luminal B tissue (75.9% and 60.8%, respectively), compared with human epidermal growth factor receptor 2- (HER2-) enriched and triple-negative breast cancer (TNBC) samples (38.2% and 18.6%, respectively)." (PMID 33134390, 2020).
acute kidney injury (4 papers, 2021 to 2024). Sudden and sustained deterioration of the kidney function characterized by decreased glomerular filtration rate, increased serum creatinine or oliguria. "For example, in cisplatin-induced acute kidney injury, overexpression of METTL14 promoted apoptosis of kidney proximal tubular cells." (PMID 34503454, 2021). "In addition, cisplatin-induced acute kidney injury in mice led to increased m6A levels and alterations in the expression of methyltransferase complexes, including METTL3, METTL14, FTO, and ALKBH541." (PMID 38297163, 2024). "Elevated levels of total renal M6A were detected in cisplatin-induced acute kidney injury (cis-AKI) in mice, accompanied by alterations in METTL3, Mettl14, WTAP, FTO and AlKBH5." (PMID 37865763, 2023).
acute lymphoblastic leukemia (4 papers, 2019 to 2024). Leukemia with an acute onset, characterized by the presence of lymphoblasts in the bone marrow and the peripheral blood. "METTL3 and METTL14 expression was reported to be downregulated in pediatric acute lymphoblastic leukemia (ALL) with ETV6/RUNX1 gene rearrangement." (PMID 33922187, 2021). "This study was aimed to explore the METTL3 and METTL14 expressions in children with ETV6/RUNX1(E/R)‐positive acute lymphoblastic leukemia (ALL) and investigate the relation between the METTL3 and METTL14 expressions with clinical features." (PMID 31429529, 2019).
asthma (4 papers, 2022 to 2025). "Although direct evidence for METTL14′s role in ferroptosis and Th2 immunity in asthma is limited, its scaffolding function is essential for guiding METTL3-mediated m6A deposition on inflammation- and epithelium-related transcripts." (PMID 41008562, 2025). "m6A methylation plays an essential role of in the pathogenesis of asthma; mRNA and protein levels of METTL14 and ALKBH5 are significantly decreased in asthma." (PMID 39011034, 2024). "In the asthma group, mRNA level of METTL14, the key methyltransferase responsible for m6A modifications, was significantly decreased compared with the control group (P=0.032)." (PMID 36250525, 2022). "In the asthma group, the mRNA and the protein level of METTL14 (the key methyltransferase) and ALKBH5 (the major demethyltransferase) were significantly decreased compared with the control group (P<0.01)." (PMID 36250525, 2022). "The results showed that the expression of known m6A writers (i.e., METTL3 and METTL14), erasers (i.e., FTO and ALKBH5), and readers (i.e., YTHDF3) was moderately downregulated in peripheral blood mononuclear cells (PBMCs) of human asthma sufferers." (PMID 37957139, 2023). "Additionally, the m6A RNA modification machinery including METTL3, METTL14, FTO, YTHDF1/2, IGF2BP2, and WTAP is explored for its emerging significance in regulating post-transcriptional gene expression during asthma progression." (PMID 41008562, 2025). "Moreover, the precise functions of METTL14, ALKBH5, and m6A methylation of IL17RB mRNA and lncRNAs in asthma need to be further elucidated." (PMID 36250525, 2022).
kidney cancer (4 papers, 2020 to 2025). Primary or metastatic malignant neoplasm involving the kidney. "For instance, METTL14 has been demonstrated to restrain the growth and metastasis of kidney cancer by reducing the expression of lncRNA NEAT1." (PMID 38528591, 2024). "Like METTL3, patients with kidney cancer are more predisposed to METTL14 mutations or CNV, and patients affected by shallow deletions of METTL14 have a poorer OS and DFS." (PMID 32765970, 2020). "Synergistic effects may occur through the interaction of EIF3A (Eukaryotic Translation Initiation Factor 3 Subunit A) and METTL14, which regulates kidney cancer progression." (PMID 32765970, 2020). "Analysis of methyltransferases in kidney cancer, including ccRCC, indicates that both METTL3 and METTL14 are tumor suppressors in this disease." (PMID 32765970, 2020).
lupus (4 papers, 2020 to 2025). "Western blot analysis showed elevated expression of the methyltransferases METTL3 and METTL14, and reduced expression of the demethylase ALKBH5 in lupus mice." (PMID 40506739, 2025). "The first available data were focused on the mRNA expression of m6A writers (METTL3, METTL14, and WTAP), erasers (FTO and ALKBH5) and readers (YTHDF2) in peripheral blood mononuclear cells (PBMCs) from lupus affected patients." (PMID 33807762, 2021).
myeloid leukemia (4 papers, 2017 to 2022). A clonal proliferation of myeloid cells and their precursors in the bone marrow, peripheral blood, and spleen. "Subsequently, methyltransferase-like 3 (METTL3), methyltransferase-like 14 (METTL14), Wilm’s tumor 1-associated protein (WTAP), and AlkB homolog 5 (ALKBH5) were reported to be related to myeloid leukemia." (PMID 35720276, 2022). "METTL14 is required for myeloid leukemia cell survival and proliferation." (PMID 31226160, 2019). "Although each of the major proteins in the m6A methylation complex—that is, RBM15, WTAP, METTL3, and METTL14—show alterations in myeloid leukemias, definitive demonstration of the role of m6A will require mechanistic evidence linking m6A alterations to leukemia phenotypes in these cancers." (PMID 28081722, 2017).
pancreatic ductal adenocarcinoma (4 papers, 2021 to 2025). An infiltrating adenocarcinoma that arises from the epithelial cells of the pancreas. "Moreover, METTL13/METTL14/WTAP complexes and YTHDF2 facilitate PIK3CB mRNA and protein expression levels, significantly promoting the proliferation and migration of PTEN-deficient pancreatic ductal adenocarcinoma cells." (PMID 39806412, 2025). "This study analyzed eight m6A regulators (METTL3, METTL14, WTAP, FTO, ALKBH5, and YTHDF1-3) in pancreatic ductal adenocarcinoma (PDAC) and found that only RNA m6A demethylase ALKBH5 serves as an independent favorable prognostic marker for this tumor." (PMID 34733841, 2021). "Interestingly, lack of METTL14 leading to increased expression of duct markers such as KRT19, SOX9, MEIS2 could have implications for pancreatic ductal carcinoma which is among the most lethal cancers in humans." (PMID 39322760, 2024).
papillary thyroid cancer (4 papers, 2020 to 2024). "METTL14 overexpression could suppress the proliferation and migration of papillary thyroid cancer cells by regulating the lncRNA OIP5-AS1 and MEK/ERK pathways." (PMID 36387210, 2022). "In papillary thyroid cancer, METTL14 regulates miR‐98 expression by inhibiting OIP5‐AS1 expression and activates epidermal growth factor receptor (EGFR), MEK/ERK pathways to inhibit proliferation and migration/invasion of papillary thyroid cancer cells." (PMID 38263865, 2024).
pulmonary arterial hypertension (4 papers, 2021 to 2025). Pulmonary arterial hypertension (PAH) is a group of diseases characterized by mean pulmonary artery pressure >20 mmHg and elevated pulmonary arterial resistance leading to right heart failure. "Down-regulation of m6A modification by knockdown of METTL3 and METTL14 can delay the progression of pulmonary hypertension by inhibiting the proliferation and migration of pulmonary arterial smooth muscle cells (Zhou X.-L." (PMID 35836571, 2022). "They further suggested inhibition of SETD2/METTL14 activity as a possible strategy for treatment of pulmonary artery hypertension in clinical settings." (PMID 35061109, 2022). "Collectively, these results demonstrated that SETD2 mediates H3K36me3 and METTL14 mediated m6A RNA modification contribute to hypoxia-induced pulmonary arterial hypertension in mice." (PMID 33658391, 2021). "This novel information partially clarified that SETD2 mediates H3K36me3 and METTL14 mediated m6A RNA modification contribute to hypoxia-induced pulmonary arterial hypertension in mice." (PMID 33658391, 2021). "In pulmonary arterial hypertension (PAH), SETD2-mediated H3K36me3 modification upregulates METTL14 expression, leading to enhanced m6A deposition." (PMID 41164187, 2025).
Wilms tumor (4 papers, 2021 to 2024). An embryonal neoplasm characterized by the presence of epithelial, mesenchymal, and blastema components. "The association between genetic variants in the METTL14 gene and Wilms tumor susceptibility remains to be fully elucidated." (PMID 34863142, 2021). "In all, in-depth mechanism of how METTL14 SNPs affects Wilms tumor risk by regulating the gene expression and splicing pattern awaits to be elucidated." (PMID 34863142, 2021). "This is the first genetic epidemiological study on the association of genetic variants in the METTL14 gene and Wilms tumor risk." (PMID 34863142, 2021). "Our results bring new insights into genetic mechanisms of how METTL14 affects Wilms tumor risk." (PMID 34863142, 2021). "Expectedly, METTL14 gene haplotypes showed a significantly increased protection against Wilms tumor, indicating the synergistic effects of these SNPs." (PMID 34863142, 2021). "Thus, we examined whether haplotypes of METTL14 gene are associated with Wilms tumor risk." (PMID 34863142, 2021). "Collectively, our results suggest that METTL14 gene SNPs may be genetic modifiers for the development of Wilms tumor." (PMID 34863142, 2021).
adenoma (3 papers, 2022 to 2023). A neoplasm arising from the epithelium. "M6A modification is regulated by RNA methyltransferase and demethylase, hence we assessed the expression of methyltransferase (METTL3, METTL14 and WTAP) and demethylase (FTO and ALKBH5) in both adenoma and CRC." (PMID 35012593, 2022). "And mRNA level of METTL14 was significantly higher in the adenoma group but not in the CRC group." (PMID 35012593, 2022).
Asthenozoospermia (3 papers, 2016 to 2025). "It was reported that m6A methylation levels and the expression of METTL3 and METTL14 were up-regulated in semen samples of patients with asthenozoospermia." (PMID 36290597, 2022). "We found that m6A content (p = 0.033) and the mRNA expression of METTL3 (p = 0.016) and METTL14 (p = 0.025) in asthenozoospermia patients were significantly higher than those of controls." (PMID 27072590, 2016). "In summary, we first reported that methyltransferases (METTL3 and METTL14), particularly METTL3, play key roles in the dynamic modification of m6A in asthenozoospermia patients and that increased m6A can impair sperm motility." (PMID 27072590, 2016). "Asthenozoospermia patients showed significantly higher mRNA expression levels of the methyltransferases, including METTL3 (p = 0.016) and METTL14 (p = 0.025) compared to the healthy controls." (PMID 27072590, 2016).
cardiac hypertrophy (3 papers, 2022 to 2023). "Taken together, we report that METTL14 regulates Akt signaling by altering m6A modification of Phlpp2 mRNA in cardiomyocytes, revealing a possible molecular mechanism underlying the role of RNA m6A modification in exercise-induced physiological cardiac hypertrophy." (PMID 36351918, 2022). "METTL14 is downregulated during exercise-induced physiological cardiac hypertrophy, while METTL14 knockdown impairs cardiac dysfunction during ischemia-reperfusion remodeling." (PMID 37273867, 2023). "MTase inactive mutant METTL14 blunted the anti-hypertrophy effects of METTL14 overexpression on exercise-induced cardiac hypertrophy." (PMID 36351918, 2022). "Though we cannot attribute the effect of exercise-induced cardiac hypertrophy to METTL14 alone, METTL14 manipulation is one of the major factors which appears essential for exercise-induced cardiac hypertrophy." (PMID 36351918, 2022). "Collectively, these data indicate that METTL14 overexpression partially abolishes exercise-induced cardiac hypertrophy." (PMID 36351918, 2022). "We reported that METTL14-mediated m6A modification was important to maintain exercise-induced physiologic cardiac hypertrophy." (PMID 36351918, 2022). "In summary, we identify METTL14 as a key methyltransferase that is involved in regulating exercise-induced cardiac hypertrophy." (PMID 36351918, 2022). "In this study, the authors report that METTL14 plays an important role in RNA m6A modification in exercise-induced physiological cardiac hypertrophy." (PMID 36351918, 2022). "Thus, cardiac m6A methylation levels, which are increased by METTL14 overexpression, are required for the effects of METTL14 to blunt exercise-induced cardiac hypertrophy." (PMID 36351918, 2022). "In vivo, wild-type METTL14, but not METTL14 mutant overexpression, inhibited physiological cardiac hypertrophy induced by exercise training." (PMID 36351918, 2022). "In vivo, wild-type METTL14 overexpression, but not MTase inactive mutant METTL14, blocks exercise-induced physiological cardiac hypertrophy." (PMID 36351918, 2022).
choroidal melanoma (3 papers, 2022 to 2025). Malignant tumor of melanocytes of the choroid. "METTL14 enhanced the invasion and migration of choroidal melanoma cells by activating Wnt/β-catenin signaling." (PMID 36835633, 2023). "Investigation of METTL14 protein expression in choroidal melanoma cells demonstrated a significant increase in C918 and MUM-2B cells (P < 0.05), supporting the association between elevated m6A expression and METTL14 upregulation in uveal melanoma." (PMID 41316357, 2025). "Our novel findings further highlight the direct binding of MAFG to METTL14, revealing that MAFG specifically binds to the promoter region of METTL14, and its heightened expression in choroidal melanoma is dependent on MAFG’s recognition of a critical motif, which triggers its specific activation." (PMID 41316357, 2025). "METTL14 was upregulated in choroidal melanoma compared to normal choroidal tissues." (PMID 36835633, 2023).